FOXL2 (forkhead box L2)
Diseases named in the same sentence as FOXL2 in open-access papers (continued):
Sharing a sentence is not in itself a finding about the gene and the disease.
thymic carcinoma (1 paper, 2022). Thymic carcinoma (TC) is a type of thymic epithelial neoplasm characterized by a high malignant potential. "However, FOXL2 was not analysed in most studies of genetic alterations in thymomas or thymic carcinomas by targeted sequencing because it is absent from NGS panels." (PMID 35884448, 2022).
thymoma (1 paper, 2022). A neoplasm arising from the epithelial cells of the thymus. "The ERBB2 and KIT variants were detected in B2B3 thymomas, and the FOXL2 variant in a micronodular thymoma with lymphoid stroma." (PMID 35884448, 2022). "In this study, 3 of 19 (16%) thymomas exhibited missense variants of uncertain clinical significance in ERBB2 [p.(Ser703Arg)], KIT [p.(Ile690Val)], and FOXL2 [p.(Pro157Ser)]." (PMID 35884448, 2022). "Because thymomas show molecular dysregulation in terms of transcription factors, we consider FOXL2 to be a molecular target meriting further investigation." (PMID 35884448, 2022). "No pathogenic variants were found in thymomas, although a few variants of uncertain clinical significance were present in KIT, ERBB2, and FOXL2." (PMID 35884448, 2022).
Zinc deficiency (1 paper, 2026). A deficiency of the essential metal Zinc; an essential cofactor for many enzymes. "Gene expression of both an oocyte-specific factor (Bmp15) and granulosa cell-specific factor (Foxl2) shown to regulate nest breakdown was decreased by zinc deficiency (p < 0.05)." (PMID 41677457, 2026).
tumor (71 papers, 2009 to 2026). "Tumor tissue of aGCT patients exhibits a FOXL2 402C>G mutation in 97%; it is a unique characteristic of this tumor type." (PMID 40507373, 2025). "We detected this ctDNA using a specific genetic alteration, the FOXL2 mutation, which is common in this tumor type." (PMID 40507373, 2025). "Whereas the TME of primary and recurrent AGCTs are frequently similar in many respects, distinct AGCT TME subtypes exist that are defined by the close association between FOXL2+ tumor cells and local COL1A1." (PMID 41042551, 2025). "Immunohistochemical analysis showed that the tumor cells expressed FOXL2 and a genetic mutation, FOXL2 c.402C>G (p.C134W), was subsequently found." (PMID 38363935, 2024). "Most potential germline pathogenic DNA repair gene variants had VAFs that were slightly higher than the somatic FOXL2 mutation, consistent with monoallelic status for both alterations in the setting of very high median tumor purity of 70% in this cohort." (PMID 38898688, 2024). "Recently, somatic mutation p.C134W in FOXL2 has been found associated with GCs tumor in adult and accounted for up to 5% of ovarian malignancies." (PMID 36793102, 2023). "The presence of this mutation is in fair agreement with IHC positivity of the tumor cells for FOXL2 expression, which allows for application of the FOXL2 expression as a surrogate IHC marker for the FOXL2p.C134W mutation." (PMID 35267514, 2022). "Because virtually all aGCTs contain the FOXL2 mutation, it would seem logical that recurrence and/or aggressive behavior would reflect other subsequent somatic genetic changes in the tumor." (PMID 35356927, 2022). "We confirmed the FOXL2 c.402C > G mutation to verify the tumor cell origin in the established cell lines and tested current and novel systemic therapies, including drug combinations to assess potential synergy." (PMID 33498451, 2021). "FOXL2 mutation status was ascertained to verify tumor cell origin of the cell lines and additional typing by snp array was performed in those lines in which the FOXL2 mutation was not present (or present in hemizygous form)." (PMID 33498451, 2021). "The precise mechanism by which this mutation promotes tumor formation is unclear; FOXL2 possibly serves as a tumor suppressor, but others have postulated that it acts as an oncogene." (PMID 32485873, 2020). "We also observed that three recurrent tumors and one primary tumor appeared to be homozygous for the FOXL2 c.402C>G mutation." (PMID 32064045, 2020). "To evaluate the role of the FOXL2 mutation and CNVs in the mechanism of recurrence, we compared primary tumor with the matching recurrent and metastatic lesions from our 4 patients." (PMID 32064045, 2020). "Subsequent studies not only independently validated the specificity of the FOXL2 mutation for adult-GCTs, but also confirmed its absence in juvenile-GCTs and in other unrelated human tumours." (PMID 28736583, 2017). "The FOXL2 gene mutation status of the six juvenile-GCT tumours was determined by direct DNA sequencing." (PMID 28736583, 2017). "Five (J1-J5) out of six patients carried the wildtype FOXL2 allele, further confirming the initial clinical diagnosis of these tumours." (PMID 28736583, 2017). "Molecular studies showed a heterozygous FOXL2 402C > G mutation in the tumor on direct gene sequencing." (PMID 28347324, 2017). "The results are also coherent with previous findings on high GATA4 or FOXL2 expression in the primary tumor associated with risk of recurrence." (PMID 24416423, 2014). "Molecular studies showed a heterozygous FOXL2 402C > G mutation in the tumor by direct gene sequencing." (PMID 25297715, 2014).
tumor (continued). "One experiment found that the use of a specific digital droplet polymerase chain reaction (ddPCR) assay could be used to find the FOXL2 mutation in circulating tumor deoxyribonucleic acid (ctDNA) in the serum of AGCT patients." (PMID 40438800, 2025). "Incorporating emerging biomarkers, such as FOXL2 mutation status or circulating tumor DNA, may also enable risk-adapted follow-up strategies and facilitate earlier detection of recurrence." (PMID 41002574, 2025). "Published data suggest that factors contributing to an increased risk of recurrence include a higher degree of nuclear pleomorphism, a mitotic rate greater than four mitoses per 10 HPF, tumor rupture, residual disease following surgery, and FOXL2 mutation expression." (PMID 39877787, 2024). "The recent discovery of mutations in DICER1, STK11 and FOXL2 genes has improved our understanding in addition to the approach to sex cord stromal tumours and can serve as diagnostic and prognostic markers and may assist in risk stratification in the future." (PMID 39430077, 2024). "It is tempting to speculate that FOXL2 mutated tumor cells continue to proliferate slowly, so relapse may ensue if all residual tumor cells are not removed by surgery or if systemic immunoediting cannot control the tumor growth." (PMID 35723333, 2022). "Overall, these data suggested that FOXL2 might be beneficial in ovarian granulosa-like tumor cell line caused by abnormal estrogen." (PMID 35163166, 2022). "However, the present study is the first to have found a change in FOXL2 mutation status between the primary tumor and the recurrent tumor." (PMID 32064045, 2020). "The presence of the FOXL2 mutation in tumors with equivocal histological diagnosis may aid in the classification of the tumor as an adult granulosa cell one." (PMID 32485873, 2020). "Cumulatively, our data underline GCT as immunologically “hot” tumor, heavily infiltrated by T cells, which can be expanded and reinvigorate in vitro, preserving their antitumor activity and their ability to target FOXL2 antigen." (PMID 32814714, 2020). "Interestingly, the mitotic count per 10 high-power fields was much higher in tumor samples that were homozygous for the FOXL2 c.402C>G mutation than in heterozygous aGCT samples." (PMID 32064045, 2020). "Although the tumor classification is robust with respect to aGCT, i.e. all contain the FOXL2 C134W mutation, the designation of stage could potentially be problematic in that a stage 1 aGCT could, for instance, be an advanced tumor caught early." (PMID 26893359, 2016). "All aGCT, whether stage 1 or advanced stage, contain the FOXL2 mutation so other genetic changes in the tumor are likely to be responsible for these differing stages and/or behaviour." (PMID 26893359, 2016). "The functional role of the pathognomonic FOXL2 mutation in GCTs is unknown, but it has been suggested to act as a tumor suppressor in granulosa cells by mediating apoptosis 40,41." (PMID 24687970, 2014). "Nevertheless, in Cox proportional hazards model, high FOXL2 associated with an increased 5 years risk of recurrence (RR 8.7, 95%CI 1.4–167.0, p = 0.018) and low FOXL2 expression with low risk for tumor recurrence in 5 years (RR 0.12, 95%CI 0.006–0.71, p = 0.018)." (PMID 24416423, 2014). "The primary screen of 752 whole genome amplified tumor DNA samples yielded 24 samples (∼4%) with a variant profile, distinct from that seen in association with the FOXL2 c.402C>G mutation-positive A-GCT specimens, as well as 41 with an indeterminate profile and 29 samples that failed." (PMID 19956657, 2009). "This recurrent tumor might have be homozygous for another FOXL2 mutation." (PMID 32064045, 2020). "However, one juvenile-GCT tumour (J6) was shown to harbour the FOXL2 mutation." (PMID 28736583, 2017).
tumor (continued). "Molecular analysis of GCT shows that a single somatic missense mutation in the forkhead transcription factor FOXL2, c.402C > G (p.Cys134Trp) is present in 70%–97% of adults with GCT and has value as a diagnostic marker for this tumour type." (PMID 41518037, 2026). "A single somatic missense mutation in FOXL2, c.402C > G (p.Cys134Trp), has previously been identified in the majority of GCT and is a pathognomonic marker for this tumour type." (PMID 41518037, 2026). "To further investigate associations between TME structure and hormone receptor expression in AGCT, we next performed a detailed analysis of ERα and PR expression across FOXL2+ AGCT tumor cells." (PMID 41042551, 2025). "According to the WHO fifth edition classification, mixed sex-cord-stromal tumors have been reintroduced, and these two tumor components typically express positive markers for sex-cord-derived tissues (such as inhibin and FOXL2)." (PMID 40901169, 2025). "Our panel included markers of tumor cells [FOXL2, ERα, PR, steroidogenic factor 1 (SF1), calretinin, and inhibin α (inhibinα)]." (PMID 41042551, 2025). "Specifically, FOXL2 was included as a key marker for AGCT tumor cell detection, with SF1, calretinin, and inhibinα serving as additional controls to validate AGCT cell staining." (PMID 41042551, 2025). "FOXL2+COL1A1− tumor cells in recurrent samples avoided other cells more frequently than in primary AGCTs." (PMID 41042551, 2025). "The first subgroup of FOXL2+COL1A1+ cells expressed other tumor markers (expression profiles highlighted by frames 1 and 2)." (PMID 41042551, 2025). "Initially, we aimed to define tumor and stromal regions based on FOXL2 and COL1A1 staining, respectively." (PMID 41042551, 2025). "First, COL1A1 staining was used to identify collagen-rich regions, followed by FOXL2 staining to define pure tumor areas." (PMID 41042551, 2025). "We noted that endothelial cells, CD8 T cells, M2 macrophages, COL1A1+ cells, and COL1A1+αSMA+ cells were most strongly avoidant of FOXL2+COL1A1− tumor cells." (PMID 41042551, 2025). "Expanding studies to investigate ERM proteins, AMH/inhibin dynamics, proliferation indices, and FOXL2 status across tumor subtypes holds promise for enhancing prognostic stratification and informing tailored postoperative management in equine practice." (PMID 41321570, 2025). "Based on this expanded analysis of IMC marker co-expression, FOXL2+COL1A1+ cells can be separated into two subgroups, one resembling FOXL2+COL1A1− tumor cells and the other with an immunophenotype resembling non-AGCT stromal cells." (PMID 41042551, 2025). "SF1 was also expressed in most AGCT tumor samples, though its staining seemed more diffuse than FOXL2; therefore, FOXL2 was used as the primary marker for tumor cell identification." (PMID 41042551, 2025). "At the same time FOXL2+COL1A1− tumor cells in AGCT-1 avoid other cells more frequently than in AGCT-2, which can suggest less infiltration level of any other cells in AGCT-1 samples." (PMID 41042551, 2025). "These FOXL2+ cells in the COL1A1+ regions frequently co-stained with other tumor markers from our IMC panel, including SF1, calretinin, and inhibinα." (PMID 41042551, 2025). "Another interesting communication involved in the development of EC is between EC cells and endometrial stromal cells with tumor-suppressor gene FOXL2 involvement." (PMID 38731868, 2024). "FOXL2 encodes Forkhead Box L2 (FOXL2), suggested to act as a tumour suppressor in granulosa cells mediating apoptosis." (PMID 36399188, 2023). "The network is based on the identification of transcription targets of FOXL2 in a human ovarian granulosa-like tumour (KGN) cell line." (PMID 36756115, 2023). "Tumor cells are typically positive for sex cord–stromal markers (FOXL2, inhibin, calretinin, SF1, WT1, CD56)." (PMID 38136408, 2023).
tumor (continued). "In this setting, thorough sampling of the tumor is essential, to look for well-differentiated tumor areas, as well as an integrated histomolecular approach (i.e., DICER1 and FOXL2 variant testing) to better classify these tumors." (PMID 38136408, 2023). "Recently, Wu J. and colleagues, using KGN human ovarian granulosa-like tumor cell line, clarified the mechanism by which estrogen feedback regulates FOXL2 to promote apoptosis." (PMID 35163166, 2022). "The tumor origin was confirmed by CytoSNP-850K snp array in the remaining two FOXL2 wild-type cell lines (GCPA096T1.II and GCPA113T1.I)." (PMID 33498451, 2021). "The copy number profiles of the FOXL2 hemizygous mutant or FOXL2 wild-type cell lines corresponded to the initial tumor, confirming tumor origin." (PMID 33498451, 2021). "Our data suggest that GCT is an immunogenic tumor that often encloses functional tumor-reactive FOXL2-specific T cells within the repertoire of expanded TILs." (PMID 32814714, 2020). "Cumulatively, these results demonstrate the therapeutic impact of FOXL2-specific T cells in 2 tumor models expressing FOXL2." (PMID 32814714, 2020). "We found that homozygosity for the FOXL2 mutation and/or the presence of chromosome instability (CIN) was predictive of early recurrence and aggressive tumor behavior." (PMID 32064045, 2020). "FOXL2-wildtype tumors harbored 2791 SNVs (median, range 1919–12,027) and FOXL2-mutant 3662 SNVs per tumor (median, range 1346–21,452)." (PMID 32455687, 2020). "We tested the therapeutic potential of FoxL2-TT vaccination and showed significant tumor control in both tumor models." (PMID 32814714, 2020). "Mice receiving the combination of vaccine and anti–PD-L1 suppressed tumor progression (FoxL2-TT plus anti–PD-L1 vs. FoxL2-TT, P = 0.0042) and improved mice survival compared with vaccination (P < 0.007) or anti–PD-L1 (P < 0.001) monotherapies." (PMID 32814714, 2020). "Combination therapy also increased FOXL2-restricted immune response in the spleen and LN and improved anti-FOXL2 T cell infiltration in the tumor." (PMID 32814714, 2020). "We performed array comparative genomic hybridization (CGH) experiments and FOXL2 genotyping by allelic discrimination on 40 tumor samples." (PMID 32064045, 2020). "Due to the lack of any suitable GCT model to test in vivo vaccine’s efficacy, we attempted to identify FOXL2 expression in several tumor cell lines." (PMID 32814714, 2020). "Addition of anti–PD-L1 to FoxL2-TT vaccination further suppressed tumor growth and improved mice survival compared with monotherapies." (PMID 32814714, 2020). "The tumor appeared to be FOXL2 C134W-positive, which corresponds to the adult-type GCT of the ovary." (PMID 30655270, 2019). "FOXL2 is the first, and probably the most striking, example of how a single gene is a critical regulator of ovarian function, morphology and neoplasia formation in humans." (PMID 29549247, 2018). "In this study, we determined the sequence of FOXL2 in a panel of tumor cell lines (NCI-60 panel, 34 established CRC cell lines, as well as the JEG-3 and KGN cell line)." (PMID 20098707, 2010). "As expected for AGCT, our IMC data showed strong nuclear FOXL2 expression across all tumor cells." (PMID 41042551, 2025). "Tumor cells were positive for α-inhibin, SF-1, FOXL2, WT-1, and Vimentin." (PMID 41584573, 2025). "We suppose that presence of FOXL2+ stromal cells in AGCTs may play a pivotal role in tumor progression and treatment response." (PMID 41042551, 2025). "We speculate that spindle-shaped FOXL2+COL1A1+ cells may behave more like fibroblasts and contribute to collagen synthesis, deposition, and remodeling of the ECM, whereas small round FOXL2+COL1A1+ cells may represent tumor cells undergoing EMT." (PMID 41042551, 2025). "Because of its risk of recurrence compared to SST, a steroid cell tumor NOS must be ruled out using FOXL2 and TFE3 immunomarkers, which are usually expressed in SST and not expressed in steroid cell tumors NOS." (PMID 38136408, 2023).